TAPBP (TAP binding protein)
Diseases named in the same sentence as TAPBP in open-access papers (continued):
Sharing a sentence is not in itself a finding about the gene and the disease.
tumor (continued). "Notably, CCL7, TAPBP, and ICAM1 were leading edge genes for all three pathways, and both CCL7 and ICAM1 were also trending up in the 14-day primary tumor proteomic analysis." (PMID 35727842, 2022). "Importantly, tumor-infiltrating DCs in G9668-treated mice displayed significantly higher mRNA levels of H-2K and H-2D heavy-chains, though not of TAPBP transcripts." (PMID 35446348, 2022). "Notably, TAPBP was significantly correlated with most immune cells (n=16) and was positively correlated with CD8 T cells, activated memory CD4 T cells and activated NK cells, which could kill tumor cells." (PMID 36311733, 2022). "Similarly, the expression of TAP2, TAPBP, PSMB8, and B2M was each shown to be induced by VC treatment in the WT, but not TET2-KO, tumor cells." (PMID 39388288, 2024).
cancer (22 papers, 2013 to 2026). A tumor composed of atypical neoplastic, often pleomorphic cells that invade other tissues. "Indeed, defective expression of TAP and TAPBP has been implicated in the loss of HLA-I expression in cancers, cancer cell lines and mouse models." (PMID 33671123, 2021). "We found that the top half of the CpGs with the highest cancer driver potential were largely predominated by CpGs of the TAPBP gene and that this gene ranked among the top 4 driver genes when methylation levels were averaged across CpGs of a given gene." (PMID 35840550, 2022). "In this work, a subset of cancer-related variants known to be in PDIA3 (ERp57) and TAPBP (tapasin) genes were collected from cBioPortal, to access data from the cancer genome atlas (TCGA) and other genomic studies." (PMID 32244998, 2020). "Downregulation of TAPBP expression has been observed for multiple cancers, including CRC, as an immune escape mechanism of human tumors." (PMID 23940558, 2013). "TAPBP plays a role in the presentation of cancer cell antigens by antigen-presenting cells." (PMID 40870972, 2025). "Furthermore, the analysis of MAX, DHX29, and TAPBP mRNA in pre-treatment and on-treatment analyses of pan-cancer patients treated with anti-PD1 therapy exhibited predictive value in discriminating PFS." (PMID 38513890, 2024). "Similarly, the altered frequencies of B2M and TAPBP came first and fourth among 484 samples from pan-cancer TCGA cohort." (PMID 36311733, 2022). "Specifically, TAP1, TAP2, TAPBP, PSMB8, and CALR were significantly upregulated in 17, 14, 13, 15, and 15 distinct cancer types, respectively." (PMID 38297270, 2024). "DDR1 expression was negatively correlated with TAPBP (MHC-related gene) in KICH, PCPG, SARC, and THCA, while positively correlated in other 19 cancers." (PMID 37031216, 2023). "MHC class I presentation of antigens on cancer cells triggers recognition by cytotoxic T-cells and destruction of the cancer cell, making TAP1 and TAPBP critical for anti-cancer immunosurveillance." (PMID 36303210, 2022). "Results showed MHC genes, including TAPBP, TAP1, and TAP2, were highly positively correlated with FANCE in most cancers." (PMID 36685883, 2022). "TAPBP is essential for effective CD8+ T cell responses to tumors and anti-cancer immune surveillance, as the presentation of major histocompatibility complex class-I antigens on cancer cells triggers the recognition and destruction of cancer cells by cytotoxic T cells (CTLs)." (PMID 38513890, 2024). "In a few cancers (particularly TCGT), CDKN2C expression was related to multiple immune-related genes, including TMEM173 (an immunostimulator), IL10RB (an immunoinhibitory), and TAPBP (a major histocompatibility complex molecule) in TGCT." (PMID 35751045, 2022).
infection (11 papers, 2013 to 2025). The state of being infected such as from the introduction of a foreign agent such as serum, vaccine, antigenic substance or organism. "The MHC-I pathway-related genes (TNF, HSP70, TAP1/2, and TAPBP) were upregulated after infection in the head kidney and spleen compared to those of the MHC-II pathway." (PMID 36835242, 2023). "Among the three peptide transporters identified, an increased expression was observed in TAP1 and TAP2 genes in cells infected with the mutant virus, while a higher expression was recorded for TAPBP during infection with the WT virus." (PMID 37513744, 2023). "Infection increased expression of the macrophage mannose receptor 1-like (MR) gene between 5 h and 8 h, the tapasin-like (TAPBP) gene at 5 h and 6 h, and the transferrin receptor 1a (TfR) gene at 4 h." (PMID 25496447, 2014). "Some of them showed an amplification of the differential regulation during the time-course of WNV-infection (early vs. mock and late vs. early), such as PPID and PCM1 (down-regulated) and TAPBP and STAT1 (up-regulated)." (PMID 23874584, 2013).
bacterial infections (1 paper, 2025). "Studies have shown that individuals with TAPBP gene mutations are more susceptible to bacterial infections, particularly from Streptococcus pneumoniae and Haemophilus influenzae." (PMID 40182927, 2025).
TAPBP also shares sentences with these, for which no sentence is quoted: adenocarcinoma (1 paper); bladder cancer (1); breast invasive carcinoma (1); Childhood onset (1); chronic hepatitis B (1); colon adenocarcinoma (1); combined immunodeficiency (1); Crohn disease (1); gallbladder cancer (1); gastrointestinal tumors (1); glioblastoma (1); graft versus host disease (1); Graves disease (1); hepatitis C (1); hypothyroidism (1); infectious disease (1); Influenza A H1N1 virus infection (1); iridocyclitis (1); major depressive disorder (1); metastatic melanoma (1); MHC) class I deficiency (1); mood disorder (1); parasitemia (1); rheumatoid arthritis (1); sarcoidosis (1); ulcerative colitis (1); vitiligo (1).